STAT3 (signal transducer and activator of transcription 3)
Diseases named in the same sentence as STAT3 in open-access papers (continued):
Sharing a sentence is not in itself a finding about the gene and the disease.
cancer (continued). "Together, these data suggest that inhibition of the gp130/STAT3 signaling axis may be applied as therapeutic measure in several entities of CRT-resistant cancers." (PMID 33530306, 2021). "Unknown multiple targets of each compound identified as an inhibitor of STAT3 signaling in this study may be involved in the putative anti-cancer property of Salvia officinalis." (PMID 33392396, 2021). "This way, the inhibitory effect of SOCS3 on JAK2 is annulled, and the subsequent activation of JAK2/STAT3 signaling enhances cancer cell growth and migration; interestingly, activated STAT3 binds to the promoter of circ-SOD2 and further promotes its expression through a positive feedback loop." (PMID 34205978, 2021). "Targeted inhibition of STAT3 acetylation may be considered as a novel epigenetic strategy for reactivation of tumor suppressor genes in human cancer." (PMID 33886682, 2021). "At the intracellular level, factors released by the tumor, its environment, or activated immune cells mediate the activity of a large variety of signaling molecules, like NF-κB, p38 MAPK, or STAT3, orchestrating inter- and intracellular signaling that ultimately promote cancer cachexia." (PMID 33419963, 2021). "First, conditioned media stimulated STAT3 activation in cancer cells." (PMID 34440697, 2021). "Importantly, STAT3 is dispensable for the growth and survival of normal cells, which makes it a valuable cancer-specific target." (PMID 34944848, 2021). "ZIP10 has also been connected to cancer progression as a marker of metastatic breast cancer, an indicator of aggressiveness of renal cell carcinoma and associated with the expression of oestrogen receptor, ERBB3 and STAT3 in clinical breast cancer." (PMID 32797246, 2021). "However, abnormal upregulation of STAT3 activity would trigger malignant transformation and cancer progression by promoting oncogenic gene expression." (PMID 34277430, 2021). "Therefore, curcumin is a versatile agent in suppressing CSC features in cancer and various molecular pathways such as Wnt, Sonic, STAT3 and NF-κB, among others, are affected to reduce CSC markers such as CD44, ALDH and CD133." (PMID 34769099, 2021). "Napa is currently being investigated in the clinic for multiple cancer indications where STAT3 signalling is believed to be important, which could result in rapid translation in PDAC." (PMID 33274592, 2021). "In several human cancers, signal transducer and activator of transcription 3 (STAT3) is palmitoylated by zinc finger DHHC-Type palmitoyltransferase 19 (ZDHHC19), a palmitoyl acyltransferase, at the SRC homology 2 (SH2) domain, which promotes its dimerization and transcriptional activation." (PMID 35004688, 2021). "Moreover, some pro-survival signals, such as FAK, AKT and STAT3, are reported to be upregulated by integrins signals in cancer cells." (PMID 34319913, 2021). "TGFβ can induce EMT in cancer cells via upregulation of STAT3, vimentin, and FN1." (PMID 33917306, 2021). "Napabucasin has an effect on stemness of cancer cells and may act through inhibition of STAT3 signaling." (PMID 33594990, 2021). "Our findings enhance the current understanding of the diverse roles of TINCR in cancer biology, and the newly identified STAT3–TINCR–EGFR-feedback loop might represent a potential therapeutic target for human cancer." (PMID 33446634, 2021). "Moreover, HNF4α can cause dysregulation of miR-122 to promote the induction of c-Met and activate the phosphorylation of STAT3, contributing to cancer aggressiveness." (PMID 33462379, 2021). "Moreover, conditioned media from P2X7R-stimulated PSCs activated the JAK/STAT3 signaling pathway in cancer cells." (PMID 34440697, 2021). "For example, JQ1 and I-BET151 exert anti-cancer functions by reducing IKBKE expression to block the NF-κB signaling pathway, although tumor-associated macrophages in TNBC confound this effect by increasing IL-6 or IL-10/STAT3/IKBKE/NF-κB axis." (PMID 34595180, 2021).
cancer (continued). "Likewise, phosphorylation of the STAT3 is correlated with the upregulation of PD-L1 in various cancers, and also cBioportal correlation data reveal the significant correlation between STAT3 and PD-L1 by spearman’s correlation coefficient (0.53)." (PMID 34440920, 2021). "Multiple studies suggest that targeting STAT3 in cancer suppresses cell growth, induces apoptosis, and enhances anticancer immune responses in vitro and in vivo, making it an attractive therapeutic target for cancer treatment." (PMID 34684783, 2021). "Several signaling pathways converge on STAT3, which is why STAT3 may be a link between cellular signaling pathways and cancer cell metabolism." (PMID 34885151, 2021). "A previous study confirmed that S1PR1 is crucial for persistent STAT3 activation in cancer." (PMID 34059068, 2021). "STAT3 dysfunction accounts for the impaired cell proliferation and apoptosis in cancer cells." (PMID 33981228, 2021). "It will be of great interest to learn whether STAT3 inhibition may thus have dual anti-cancer benefits." (PMID 34759824, 2021). "p-STAT3 expression was observed not only in cancer cells but also in the myeloid cells." (PMID 33922837, 2021). "For example, garcinol, obtained from Garcinia indica and several other Garcinia plants, exhibits excellent cytotoxicity and anti-tumorigenesis activity by inhibiting various key signaling pathways involved in cell survival and proliferation of cancer cells, such as NF-κB and STAT3." (PMID 34638708, 2021). "However, previous works by our group and others have indicated that the STAT3 pathway is important in cancer cachexia in the muscle." (PMID 34175899, 2021). "Moreover, the combination of STAT3 and cyclin D2 promoter promotes the continuous growth of cancer stem cells." (PMID 33788424, 2021). "Importantly, IL-6 has been demonstrated to have a strong impact on the early progression to carcinoma in IBD via STAT3 signaling." (PMID 34884543, 2021). "Moreover, STAT3 is constitutively active in various carcinomas, including colon, prostate, breast, and lung carcinomas." (PMID 34513827, 2021). "Different downstream targets of STAT3 have been identified in cancer and it has also been shown that microRNA (miR), long non-coding RNA (lncRNA) and other molecular pathways are able to function as upstream mediators of STAT3 in cancer." (PMID 32545648, 2020). "Therefore, inhibition of STAT3 significantly abolishes the formation of cancer stem-like tumorspheres." (PMID 33023006, 2020). "Therefore, targeting STAT3 is a potentially valuable strategy for cancer therapy, and several STAT3 inhibitors have been developed, some of which are under clinical trials." (PMID 32183406, 2020). "Finally, the anti-cancer efficacy of AT-I in CRC is essentially mediated by inactivation of the JAK2/STAT3 signaling pathway." (PMID 32273843, 2020). "Therefore, targeting the STAT3 signaling pathway has emerged as a promising therapeutic strategy for numerous cancers." (PMID 32972405, 2020). "It has now become evident that dysregulated STAT3, vital for the expression and functioning of genes required for cell survival and development, including immunity and stemness, is a crucial target to overcome the cancer pathogenesis and related challenges." (PMID 32182833, 2020). "Therefore, the inactivation of STAT3 has been considered as a promising cancer therapeutic strategy." (PMID 32150979, 2020). "In addition, constitutively active non-receptor tyrosine kinases (nRTKs) like SRC or ABL facilitate STAT3 activation in cancer." (PMID 32365499, 2020).
cancer (continued). "STAT3 promotes aerobic glycolysis by increasing glucose consumption and lactate production in oral squamous cell carcinoma cells, thus inducing the migration and invasion of cancer cells, as well as the epithelial-mesenchymal transition process." (PMID 33003453, 2020). "In this type of cancer, TAMs clearly overexpress interleukin-8 (IL-8) and growth-regulated oncogene (GRO) chemokines, which are associated with epithelial-to-mesenchymal transition CSC-like phenotypes through the activation of JAK2/STAT3 signaling." (PMID 32488850, 2020). "Our previous work has demonstrated that DYRK1A positively regulates EGFR/Met via regulating the expression and activation of STAT3, and that suppression of DYRK1A enhances the anti-cancer activity of EGFR-TKIs in wild-type EGFR NSCLC cells via inhibiting the STAT3 signaling pathway." (PMID 32587776, 2020). "STAT3, NF-κB, and MAPK are crucial inflammation and cancer-associated pathways." (PMID 32550901, 2020). "Interestingly, it has ben reprted that STAT3 can bind to PD-L1 promoter in cancer cells, then induce immunosuppression by regulating PD-1/PD-L1 expression." (PMID 32486001, 2020). "STAT3 signaling also appears to show a relationship with an aggressive course of cancer." (PMID 32488850, 2020). "Resveratrol was an effective treatment in constitutively active STAT3 cancer cells." (PMID 32731620, 2020). "Moreover, PP affects diverse signaling pathways associated with cancer cell growth and survival, including mitogen-activated protein kinase (MAPK), PI3K/Akt, and STAT3 pathways." (PMID 31948057, 2020). "Many studies have revealed that the constitutive activation of STAT3 is common in human cancers." (PMID 32911343, 2020). "The STAT3 pathway is commonly activated in cancer, driving cell proliferation and metastasis." (PMID 32823952, 2020). "STAT3 interacts with G9a and STAT3-G9a-mediated epigenetic silencing promotes cancer progression." (PMID 32879309, 2020). "We recently identified ODZ10117 as a small molecule inhibitor of STAT3 and suggested that it may have an effective therapeutic utility for the STAT3-targeted cancer therapy." (PMID 32183406, 2020). "These preclinical data suggest that agents and approaches that block the activation of STAT3 in cancer cells could have a substantial additional value in improving the sensitivity to anti-cancer drugs or preventing anti-cancer drug resistance." (PMID 31963556, 2020). "STAT3 induces the expression of multiple genes related to cancer cell growth and survival, and also could activate cap‐dependent translation through MLST8 expression, further promoting cancer cell proliferation." (PMID 32495998, 2020). "Our data suggest that betavulgarin, which targets Sox2/Stat3 signaling, might be used as an anti-cancer agent." (PMID 32630026, 2020). "Macrophage-dependent efferocytosis of apoptotic cancer cells drives NF-κB and Stat3 transcriptional machinery to promote pro-inflammatory cytokine production that may lead to skeletal metastases." (PMID 32326073, 2020). "Moreover, STAT3-mediated EMT stimulation mediates resistance of cancer cells into cisplatin chemotherapy." (PMID 32784711, 2020). "In addition, a constitutive expression of IDO in human cancer is sustained by an autocrine signal mediated via STAT-3 activation by proinflammatory cytokine IL-6 and AHR activation by tryptophan catabolites such as kynurenine." (PMID 32384638, 2020). "Importantly, over-activation of STAT3 induces the transcription of various genes involved in cellular survival, inflammation, epithelial to mesenchymal transition, and cancer stem cell maintenance, all of which promote tumor progression." (PMID 33138914, 2020). "Additionally, several direct intracellular interactions between CD44 and STAT3 have been reported across different cancer models." (PMID 33335857, 2020). "Then we analyzed the activation of STAT3 and other cancer-related pathways." (PMID 32041943, 2020).
cancer (continued). "The loss of negative STAT3 regulators is observed in multiple cancers, which promote STAT3 hyperactivity." (PMID 33003453, 2020). "Finally, we can control some of STAT3 cancer progression through inhibition of the S100B-RAGE pathway." (PMID 32443845, 2020). "Therefore, inhibiting the STAT3 signaling is a promising therapeutic way for developing anti-cancer drugs." (PMID 32549792, 2020). "As both STAT3 and STAT5 are implicated in HPV infection and HPV-associated cancers, the inhibition of these pathways may inhibit viral replication and be beneficial in the prevention or treatment of these cancers." (PMID 32899142, 2020). "Since NONO is associated with the clinical outcomes in cancer patients, and STAT3 is regulated by NONO and is involved in its function, we investigated the clinical relevance of STAT3 in samples from BC patients." (PMID 32724453, 2020). "Luteolin can also regulate IL-6 production, by binding competition to IL-6Rα receptor, that causes the reduction of signal transducer and activator of transcription 3 (STAT3) phosphorylation, responsible for the transcription of different genes involved in cancer initiation and progression." (PMID 32110931, 2020). "Importantly, the data provide a new insight into the combination of immunotherapy and STAT3 related inhibitors in clinical cancer treatment." (PMID 32486001, 2020). "In addition, constitutive STAT3 activation was reported to be involved in the formation of CRC-derived cancer stem-like tumorspheres." (PMID 33023006, 2020). "It has been shown that STAT3 was aberrantly activated or overexpressed in many types of cancers." (PMID 31949495, 2020). "The molecular pathways allowing the survival of cancer cells target STAT3." (PMID 32545648, 2020). "Therefore, targeting STAT3 using direct small molecule inhibitors serves as a good strategy to counteract the deleterious effects of STAT3 in cancer cells." (PMID 32967366, 2020). "STAT3 is a key molecule in the antiapoptotic pathway important in many cancers." (PMID 32071920, 2020). "Thus, inhibition of STAT3/5 substantially supports replication and viral particle production in cancer cells." (PMID 32046095, 2020). "Moreover, the interactions between NF-κB and STAT3 signaling pathways were discovered in various physiological and pathological processes, such as B-cell activation, cancer cell starvation, and mitochondrial fusion." (PMID 33041664, 2020). "In addition to its positive role in cancer cell survival, mitochondrial STAT3 contributes to Ras-dependent cellular transformation by promoting ETC activity, particularly with respect to complexes II and V." (PMID 33003453, 2020). "LOB3 also suppressed the motility of C6 cells, which is critical for cancer cell migration, invasion, and metastasis, by inhibiting actin polymerization, and LOB3 suppressed the activation of Src and STAT3, which are proto-oncogenic factors activated by actin polymerization in cancer cells." (PMID 33322712, 2020). "Numerous studies have reported that phosphorylation at a single tyrosine residue (Y705) in the transactivation domain of STAT3, by Janus associated kinase (JAK) or c-Src, results in the proliferation and maintenance of multiple cancers including HNSCC and correlates with lower survival rates." (PMID 33206698, 2020). "A recent study demonstrated that efferocytosis of apoptotic cancer cells activates NF-κB and STAT3 transcriptional machinery to promote the production of the pro-inflammatory C-X-C motif chemokine 5 (CXCL5) in the bone microenvironment, which supported prostate cancer skeletal metastasis." (PMID 32326073, 2020). "Furthermore, NO also targets another SASP factor, the signal transducer and activator of transcription 3 (STAT3), an important target in cancer therapy and a key kinase involved in the IL-6 signaling pathway." (PMID 32370259, 2020).
cancer (continued). "Other studies have shown that pimozide treatment could also reduce Wnt/β-catenin signalling and STAT3 phosphorylation in other types of cancer, such as HCC and prostate cancer." (PMID 32872372, 2020). "Interestingly, downstream pathway analysis reveals a difference in STAT3 transcriptional influence of the adipocytokine signaling pathway in mammary gland derived cancer models, MCF-7 and MDA-MB-468; the latter generally considered a metastatic model." (PMID 32331320, 2020). "Furthermore, CAFs per se can also serve as a source of paracrine factors acting on cancer cells to activate STAT3." (PMID 32752017, 2020). "We postulate that the translocation of phosphorylated STAT3 (Ser727) to the mitochondria could be an important signal initiator in cancer cell metabolism." (PMID 33003453, 2020). "In addition, the critical role of STAT3 in the development of both solid and hematological human malignancies has been reported by many research groups." (PMID 32182833, 2020). "Inhibition of STAT3 by anti-cancer agents is important in effective HCC therapy." (PMID 32992587, 2020). "IPA of the 37 plasma-derived sEV protein features with ROC AUCs ≥ 0.70 revealed NKX3-1 (p = 1.4 × 10−9) as a top causal network, Cancer, Cell Death and Survival as a top disease function (p = 1.57 × 10−8) and AHR, VEGF, EGF, IRF1 and STAT3 as predicted significant upstream regulators." (PMID 32370304, 2020). "Besides the inhibition of the JAK/STAT signaling pathway, resveratrol was also found to suppress the function of Src tyrosine kinase, which consequently blocked STAT3’s action in specific cancer cells." (PMID 32545187, 2020). "In addition to mediating glycolysis, STAT3 activation is also involved in the proliferation and anti-apoptosis of cancer cells." (PMID 32273843, 2020). "Targeting the STAT3/NF-kB axis is a potential strategy in cancer therapy." (PMID 32545648, 2020). "Moreover, IL-10 was reported to play important role in cancer development and to strongly induce the phosphorylation of STAT3 in cancer cells." (PMID 33372604, 2020). "STAT3-PD-L1 axis plays a key role in cancer immunosuppression." (PMID 32483429, 2020). "However, STAT3 is constitutively activated in several human cancers and plays crucial roles in promoting cancer cell proliferation and survival." (PMID 33371351, 2020). "STAT3 activation not only promotes cell growth and survival but also induces resistance to conventional therapies that rely on apoptotic machinery to eliminate cancer cells." (PMID 33038921, 2020). "In addition, activation of the LKB1/AMPK pathway by metformin which is the first-line treatment for type 2 diabetes, suppresses IL-6-induced STAT3 expression and NF-κB activation in various cancers." (PMID 31952344, 2020). "Given the essential roles of STAT3 in development, immunity, tissue stress and cancer, addressing these questions could have important implications for the diagnosis, treatment and understanding of a wide spectrum of human pathologies." (PMID 32123861, 2020). "Moreover, it has been reported that EphA2 promotes cancer progression by pS897-EphA2-activating AKT/Stat3 signaling." (PMID 32848131, 2020). "STAT3 has been reported to maintain the survival of cancer cells." (PMID 33024090, 2020). "Mitochondrial function and STAT3 are intricately linked, and recently two novel STAT3 inhibitors, OPB-51602 and OPB-111077, were found to be inhibitors of mitochondrial oxidative phosphorylation and able to resensitize cancer cells to tyrosine kinase inhibitors." (PMID 32863208, 2020). "It is held that targeting the lncRNA/STAT3 axis is of importance in cancer therapy." (PMID 32545648, 2020). "Recent studies have reported that STAT3 might play a crucial role in maintaining glycolysis in cancer cells by regulating HK2." (PMID 32273843, 2020). "Thus, the current study aimed to elucidate the precise molecular mechanism underlying Nar anti-cancer function, especially regarding its influence on JAK2/STAT3 signaling pathway." (PMID 33680016, 2020).